Y_RNA (Y RNA )
Gene: Miscellaneous RNA gene on chromosome 7 (75,381,638 to 75,381,739, forward strand). Ensembl gene ENSG00000275930.
Homologues: Orthologues: macaque Y_RNA (85% identical), guinea pig Y_RNA (83% identical), dog Y_RNA (75% identical). Paralogues in human: Y_RNA (100% identical), Y_RNA (95% identical), RNY3 (86% identical), Y_RNA (86% identical), RNY3P1 (85% identical), Y_RNA (85% identical), Y_RNA (84% identical), RNY3P14 (83% identical), Y_RNA (83% identical), Y_RNA (82% identical), RNY3P5 (81% identical), Y_RNA (81% identical), and 97 more.